SLC25A11 (solute carrier family 25 member 11)
Diseases named in the same sentence as SLC25A11 in open-access papers:
SLC25A11 is named in the same sentence as 30 diseases in open-access papers, as found by Europe PMC text mining. Sharing a sentence is not in itself a finding about the gene and the disease. The quoted sentences say what the papers report.
melanoma (6 papers, 2019 to 2025). A malignant, usually aggressive tumor composed of atypical, neoplastic melanocytes. "The carcinogenic effect of SLC25A11 has been confirmed in lung adenocarcinoma, melanoma, and hepatocellular carcinoma." (PMID 36514121, 2022). "Increased expression of SLC25A11 was reported for melanomas in a proteomics study that analyzed 61 primary melanomas." (PMID 31781212, 2019).
cardiomyopathy (3 papers, 2022 to 2025). A disease of the heart muscle or myocardium proper. "Downregulated proteins in the aged group (TUBGCP2 and SLC25A11) were enriched in cytoskeletal dynamics and cardiomyopathy pathways, whereas upregulated proteins (ATP6V0D2 and TPM1) associated with oxidative stress and neurodegenerative disorders." (PMID 40662159, 2025). "FUNDC2 knockout protects mice from DOX-induced cardiomyopathy by preventing ferroptosis, and SLC25A11 knockdown reduces mitoGSH to prevent erastin-induced ferroptosis in FUNDC2-KO cells." (PMID 39872359, 2022). "Prominently downregulated proteins (TUBGCP2, NPR2, MT-ATP6, SLC25A11, and so on) were enriched in cytoskeletal dynamics and cardiomyopathy pathways, while upregulated proteins (ATP6V0D2, HNRNPA1, TPM1, and so on) associated with oxidative stress responses and neurodegenerative disorders (AD and PD)." (PMID 40662159, 2025). "Conversely, the downregulation of cardiomyopathy-related proteins (NPR2 and SLC25A11) aligns with blood-based findings of declining cardiac markers in aging, suggesting conserved cross-tissue aging mechanisms." (PMID 40662159, 2025). "In the context of doxorubicin (DOX)-induced cardiomyopathy, FUNDC2 has been shown to interact with SLC25A11, leading to decreased stability of SLC25A11 and downregulation of mitochondrial GSH, ultimately promoting ferroptosis." (PMID 37548939, 2024). "Recently, it has been reported that FUNDC2 regulates ferroptosis by interacting with the mitochondrial glutathione transporter SLC25A11 to negatively regulate mitoGSH levels, and that it contributes to doxorubicin (DOX)-induced cardiomyopathy." (PMID 39872359, 2022).
non-small cell lung carcinoma (3 papers, 2020 to 2025). A group of at least three distinct histological types of lung cancer, including non-small cell squamous cell carcinoma, adenocarcinoma, and large cell carcinoma. "Additionally, loss of the enzyme catalyzing these reactions (encoded by SLC25A11) inhibits tumor cell growth in non-small cell lung cancer." (PMID 33424926, 2020).
paraganglioma (3 papers, 2019 to 2025). A benign or malignant neoplasm arising from paraganglia located along the sympathetic or parasympathetic nerves. "Consistent with the mRNA data, SLC25A11 protein levels were markedly reduced in pheochromocytoma and paraganglioma samples carrying the germline SLC25A11 c.293G>A variant compared to other tumors." (PMID 40242210, 2025). "Recent studies have identified germline pathogenic variants in the SLC25A11 gene in patients with paragangliomas and metastatic disease." (PMID 40242210, 2025). "In addition to moderate to strong SDHB staining, we observed an absence of immunostaining for 5hmC in all 3 tumors, indicating a hypermethylated tumor profile, which is characteristic of tumors associated with SDHx defects and paragangliomas in patients harboring pathogenic variants in SLC25A11." (PMID 40242210, 2025). "Consistent with the mRNA findings, SLC25A11 protein levels were markedly reduced in the pheochromocytoma and paraganglioma compared to other tumors." (PMID 40242210, 2025). "A heterozygous missense variant in SLC25A11 (c.715C>A/p.Pro239Thr) was first identified in a 46-year-old patient with a non-secreting abdominal paraganglioma, which exhibited a cluster 1A molecular profile in the absence of pathogenic variants in SDHx or FH." (PMID 40242210, 2025).
hepatocellular carcinoma (2 papers, 2022 to 2024). A malignant tumor that arises from hepatocytes. "Similarly, Pan also showed that patients with hepatocellular carcinoma with a high expression of SLC25A11 had a better prognosis." (PMID 36514121, 2022).
liver cancer (2 papers, 2020 to 2021). An epithelial or non-epithelial malignant neoplasm that arises from the liver. "In conclusion, this study identified that SLC25A11 serves as a new prognostic marker for liver cancer." (PMID 32555317, 2020). "The results showed that SLC25A11 mRNA was downregulated in liver cancer (P = 0.0019), which was also verified by the GSE54236 and HCCDB databases." (PMID 32555317, 2020). "Liver cancer patients with low SLC25A11 expression had shorter OS and RFS than patients with high SLC25A11 expression." (PMID 32555317, 2020). "Both univariate and multivariate Cox analyses revealed that SLC25A11 played an important role in OS and RFS, which means that SLC25A11 is a novel independent prognostic factor in liver cancer." (PMID 32555317, 2020). "In this study, we demonstrated that SLC25A11 was low expressed in liver cancer by analyzing data from the TCGA." (PMID 32555317, 2020). "The Cancer Genome Atlas database was used to analyze the levels of SLC25A11 in liver cancer." (PMID 32555317, 2020). "The purpose of this research was to investigate the prognostic value of SLC25A11 in liver cancer." (PMID 32555317, 2020). "Our results demonstrated that SLC25A11 could be a reliable marker for diagnosis and a predictor of prognosis in liver cancer." (PMID 32555317, 2020). "Our results revealed that SLC25A11 was downregulated in liver cancer compared to normal controls." (PMID 32555317, 2020). "ROC analysis suggested that SLC25A11 could be regarded as a marker in the diagnosis and prognosis of liver cancer." (PMID 32555317, 2020). "However, we found that SLC25A11 was expressed at low levels in liver cancer." (PMID 32555317, 2020). "We found that SLC25A11 could be regarded as a prognostic factor for poor survival in liver cancer." (PMID 32555317, 2020). "Thus, SLC25A11 may serve as a prognostic marker for liver cancer." (PMID 34912753, 2021). "Furthermore, we postulate that SLC25A11 plays an essential role in transporting NADH and GSH from the cytoplasm into mitochondria, providing energy for liver cancer cells to withstand harsh environments." (PMID 32555317, 2020). "However, the prognostic significance of SLC25A11 expression in liver cancer has not yet been determined." (PMID 32555317, 2020).
neuroendocrine tumors (2 papers, 2020 to 2025). "We then aimed to determine whether the germline variant of uncertain significance (VUS) c.293G>A in SLC25A11 could be implicated in the development of neuroendocrine tumors in the patient with CSS." (PMID 40242210, 2025).
pheochromocytoma (2 papers, 2022 to 2025). "Cluster 1 PPGLs include pheochromocytomas and abdominal paragangliomas carrying the highest risk of metastatic spread, especially the TCA cycle aberrant tumors carrying genetic variants in enzymes regulating the TCA cycle, including SDHA, SDHB, SDHAF2, FH, MDH2, ISH1 and SLC25A11." (PMID 35205664, 2022).
abdominal aortic aneurysm (1 paper, 2025). Enlargement and ballooning of the vessel that supplies arterial blood to the abdomen, pelvis and legs. "During abdominal aortic aneurysm (AAA) formation, NETs affect the stability of the mitochondrial carrier protein SLC25A11." (PMID 40356926, 2025).
cutaneous melanoma (1 paper, 2017). A primary melanoma arising from atypical melanocytes in the skin. "Then, we accessed the cBioPortal for Cancer Genomics to evaluate and correlate mRNA levels of FAH and the oxoglutarate/malate carrier SLC25A11 in cutaneous melanoma data from TCGA." (PMID 29371990, 2017).
glioblastoma (1 paper, 2025). The most malignant astrocytic tumor (WHO grade IV). "Indeed, inhibition of SLC25A11 in glioblastoma cells resulted in reduced cell viability, energy depletion, and mitochondrial dysfunction, highlighting the potential of targeting this gene as a therapeutic strategy for MAS inhibition in GBM treatment." (PMID 40405188, 2025).
hamartoma (1 paper, 2023). A benign and excessive tumor-like growth of mature cells and normal tissues which grow in a disorganized pattern. "Hamartoma and neoplasm of the eye were associated with KRT1, VHL and SLC25A11." (PMID 37185447, 2023).
ischemic stroke (1 paper, 2016). A stroke disorder caused by obstruction of blood flow to the brain, due to thrombotic (local blood clot formation) or embolic (due to a blood clot or other material traveling from another site) event. "One of these, the SLC25A11, plays an important role in several metabolic processes and appears to be downregulated in ischemic stroke." (PMID 27711126, 2016).
metastatic disease (1 paper, 2025). "Germline SLC25A11 variants were identified in 6 additional patients in a validation cohort of 639 PPGLs, 5 of whom had metastatic disease." (PMID 40242210, 2025). "Genetic alterations in SLC25A11 have been associated with a higher risk of metastatic disease in 70% of the patients." (PMID 40242210, 2025). "In conclusion, a rare germline deleterious variant in SLC25A11 was identified in a patient with CSS, who had a poor outcome due to metastatic disease." (PMID 40242210, 2025).
Sepsis (1 paper, 2021). Sepsis is defined as life-threatening organ dysfunction caused by a dysregulated host response to infection. "Deciphering the impact of O-GlcNAcylation on Slc25a11 may lead to a better understanding of the impairment of mitochondrial metabolism during sepsis." (PMID 34502162, 2021).
tumor (13 papers, 2020 to 2025). "Strikingly, a marked reduction in SLC25A11 expression was detected in tumor samples carrying the c.293G>A variant (0.69 ± 0.003) compared to cluster 1 (1.39 ± 0.45; P = .0229) and cluster 2 tumors (1.79 ± 0.71; P = .0154)." (PMID 40242210, 2025). "In most of these patients with germline SLC25A11 mutations, a loss of heterozygosity was also reported, thus suggesting a role of SLC25A11 as a tumor-suppressor gene." (PMID 39000254, 2024). "This phenotype seems to be involved in tumor progression and mutations in the FH, SLC25A11, and MDH2 genes along with SDHB and SDHD mutations can be considered to be a risk factor for PPGL malignancy." (PMID 34833055, 2021). "Furthermore, SLC25A11 (encoding the oxoglutarate carrier OGC) is a tumor-suppressor gene (together with some genes encoding TCA cycle enzymes), i.e., mutations of SLC25A11 confer a predisposition to metastatic paragangliomas." (PMID 32340404, 2020). "Our research found that OTUD1 stabilizes the mitochondrial protein SLC25A11, elevating ROS levels and inducing oxidative stress, which leads to tumor cell apoptosis." (PMID 40664662, 2025). "SLC25A members are crucial for tumor immune and energy metabolism in PC, and SLC25A11, SLC25A29, and SLC25A44 can be used as favorable prognostic markers." (PMID 36514121, 2022). "Several studies reported germline mutations in other susceptibility genes for PPGLs, such as FH, SLC25A11, and MDH2, which were associated with aggressive tumor behavior." (PMID 34833055, 2021). "Univariate Cox analysis identified the potential RFS-related variables, including the stage, T classification, residual tumor status and SLC25A11." (PMID 32555317, 2020). "Univariate Cox analysis identified the potential OS-related variables, including the stage, T classification, residual tumor status and SLC25A11." (PMID 32555317, 2020). "LOH for SLC25A11 was observed in 4 cases where tumor samples were available." (PMID 40242210, 2025). "Overall, these findings indicate that KN612 inhibits tumor invasion by suppressing SLC25A11 expression, suggesting that SLC25A11 may plays an important role in promoting tumor growth." (PMID 40405188, 2025). "We aimed to determine whether a second somatic event could explain the reduced levels of SLC25A11 observed in the tumor samples from the patient with CSS." (PMID 40242210, 2025). "Multivariate Cox analyses showed that SLC25A11 expression (HR value: 1.526, 95% CI: 1.072–2.172, P = 0.019), residual tumor status (HR value: 1.410, 95% CI: 1.103–1.801, P = 0.006), and T classification (HR value: 1.835, 95% CI: 1.458–2.310, P < 0.001) were independent predictors of poor OS." (PMID 32555317, 2020). "Multivariate Cox analyses showed that SLC25A11 expression (HR value: 1.604, 95% CI: 1.145–2.246, P = 0.006), residual tumor status (HR value: 1.300, 95% CI: 1.021–1.655, P = 0.034), and T classification (HR value: 1.671, 95% CI: 1.287–2.169, P < 0.001) were independent predictors of poor RFS." (PMID 32555317, 2020). "This suggests that targeting SLC25A11 may suppress tumor progression in GBM." (PMID 40405188, 2025). "They further demonstrated that SLC25A11 could serve as a novel tumor suppressor gene." (PMID 36514121, 2022). "Therefore, the association of the expression of SLC25A11 with poor survival may be due to the effect of SLC25A11 on tumor energy metabolism." (PMID 32555317, 2020). "Research indicates that SLC25A11, a mitochondrial Glutathione (GSH) transporter, regulates ROS levels to influence cellular metabolism and tumor proliferation, contributing significantly to oxidative stress regulation in various cancers." (PMID 40664662, 2025). "Tumor immune analysis revealed that SLC25A11 and SLC25A29 are involved in opposing tumor immunity together." (PMID 36514121, 2022). "The correlation between SLC25A11, SLC25A29, and SLC25A44 mRNA expression levels and tumor immune invasion was further explored in PC." (PMID 36514121, 2022).
tumor (continued). "According to co-expression network studies, SLC25A11, SLC25A29, and SLC25A44 were involved in the energy metabolism of PC and prevented tumor growth, invasion, and metastasis." (PMID 36514121, 2022). "Additionally, the results of immune infiltration analysis showed that the expression of SLC25A11 was positively correlated with the recruitment of immune cells, such as CD8 + T, CD4 + T, and DC, which alludes that SLC25A11 may also play a role in anti-tumor immunity." (PMID 36514121, 2022). "Additionally, we used the Integrative Genomics Viewer (IGV) software to visualize the reads mapped to the SLC25A11 locus, allowing us to investigate any coverage gaps that could indicate potential alterations in the whole-exome sequencing data from the germline and 3 tumor samples." (PMID 40242210, 2025). "In the absence of IR, upregulating OTUD1 or silencing SLC25A11 did not significantly affect tumor growth." (PMID 40664662, 2025). "Interestingly, SLC25A11, SLC25A29, and SLC25A44 were significantly overexpressed in ductal, acinar and endocrine cells in tumor tissues compared with normal tissues (P < 0.001)." (PMID 36514121, 2022). "As shown, of the various tumor pathological grades, the expression levels of SLC25A4 (P < 0.01), SLC25A11 (P < 0.0001), SLC25A24 (P < 0.01), SLC25A37 (P < 0.01), SLC25A42 (P < 0.01), SLC25A43 (P < 0.0001), SLC25A44 (P < 0.05) and SLC25A45 (P < 0.05) were significantly different." (PMID 36514121, 2022).
cancer (12 papers, 2014 to 2025). A tumor composed of atypical neoplastic, often pleomorphic cells that invade other tissues. "SLC25A11 knockdown significantly reduced ATP production and inhibited cancer cell proliferation by blocking the mTOR phosphorylation and downregulation of c-Myc and eIF4B." (PMID 36902385, 2023). "Although N-phenylamide (KN612), a SLC25A11 inhibitor, has been shown to interfere with cancer growth by reducing ATP production in several studies, its effect and mechanism in GBM remain unclear." (PMID 40405188, 2025). "Additionally, SLC25A11 knockdown inhibited cancer cell proliferation by reducing ATP production by 80% and induced cell cycle arrest in lung and melanoma cancer cells." (PMID 40405188, 2025). "The expression level of SLC25A11 is closely related to cancer." (PMID 36902385, 2023). "SLC25A11 increases mitochondrial membrane potential in cancer cells." (PMID 36902385, 2023). "Moreover, SLC25A11 is essential for ATP generation in cancers as it regulates NADH transportation from the cytoplasm to mitochondria." (PMID 32555317, 2020). "In addition, five genes involved in the 47-mRNA metastasis-related model, including FABP4, GUCY2C, MEIS2, POU1F1, and SLC25A11 have been reported to be related to the metastasis of other human cancers." (PMID 33159021, 2020). "Intriguingly, SLC25A11 and SLC25A29 have also been reported to be involved in cancer progression by affecting mitochondrial function." (PMID 37550282, 2023). "SLC25A11 has been proven to be a crucial transporter of NADH from the cytoplasm to mitochondria in the ATP production process, especially in cancer cells." (PMID 32555317, 2020). "This implies that SLC25A11 is necessary for embryogenesis but not for the proliferation of differentiated cells, which suggests that it can be a good marker for cancer." (PMID 32555317, 2020).
SLC25A11 also shares sentences with these, for which no sentence is quoted: fibrosis (2 papers); Carney-Stratakis syndrome (1); head and neck paraganglioma (1); idiopathic pulmonary fibrosis (1); insulinoma (1); ischemia (1); liver fibrosis (1); lung adenocarcinoma (1); lung carcinoma (1); nasopharyngeal carcinoma (1); neoplasm of the eye (1); retinal disease (1); type 2 diabetes (1).